RN7SKP79 (RN7SK pseudogene 79)
Gene: Miscellaneous RNA gene on chromosome 5 (6,848,127 to 6,848,462, reverse strand). Ensembl gene ENSG00000200243.
Homologues: Orthologues: chimpanzee 7SK (97% identical), guinea pig 7SK (57% identical). Paralogues in human: RN7SKP71 (76% identical), 7SK (74% identical), RN7SKP255 (74% identical), RN7SKP90 (74% identical), RN7SKP3 (74% identical), RN7SKP203 (73% identical), RN7SKP180 (72% identical), RN7SKP294 (72% identical), RN7SKP176 (72% identical), RN7SKP189 (72% identical), RN7SKP9 (72% identical), RN7SKP124 (71% identical), and 284 more.